THEMIS (thymocyte selection associated)
Description:
Plays a central role in late thymocyte development by controlling both positive and negative T-cell selection. Required to sustain and/or integrate signals required for proper lineage commitment and maturation of T-cells. Regulates T-cell development through T-cell antigen receptor (TCR) signaling and in particular through the regulation of calcium influx and phosphorylation of Erk.
Synonyms: C6orf190; C6orf207; bA325O24.4; FLJ40584; bA325O24.3; THEMIS1; GASP; SPOT; TSEPA
Tractability: PROTAC: ubiquitination databases record sites on it; its protein half-life has been measured.
Gene: Protein-coding gene on chromosome 6 (127,708,072 to 127,918,631, reverse strand). Ensembl gene ENSG00000172673.
Subcellular location: Cytoplasm; Nucleus
Subcellular location (Human Protein Atlas): Cytosol; Nucleoplasm
Gene Ontology:
Molecular function: protein binding
Biological process: negative T cell selection; positive T cell selection; T cell receptor signaling pathway
Cellular component: COP9 signalosome; cytoplasm; nucleus; cell-cell junction
Genetic constraint (gnomAD): Loss-of-function variants: 35 observed, 51.9 expected, observed/expected ratio (o/e) 0.67, 90% interval 0.51 to 0.89. The upper end of that interval is the gene's LOEUF score, 0.89, which puts it in group 3 of 6, group 1 being the genes least tolerant of losing a copy. Missense variants: 792 observed, 791.61 expected, observed/expected ratio (o/e) 1, 90% interval 0.94 to 1.06. Synonymous variants: 289 observed, 283.04 expected, observed/expected ratio (o/e) 1.02, 90% interval 0.93 to 1.13.
Homologues: Orthologues: chimpanzee THEMIS (99% identical), macaque THEMIS (97% identical), dog THEMIS (88% identical), pig THEMIS (88% identical), rabbit THEMIS (83% identical), guinea pig THEMIS (80% identical), mouse Themis (79% identical), rat Themis (79% identical), tropical clawed frog themis (48% identical), zebrafish themis (37% identical). Paralogues in human: THEMIS2 (31% identical).
Diseases named in the same sentence as THEMIS in open-access papers:
THEMIS is named in the same sentence as 23 diseases in open-access papers, as found by Europe PMC text mining. Sharing a sentence is not in itself a finding about the gene and the disease. The quoted sentences say what the papers report.
autoimmune disease (3 papers, 2018 to 2025). A disorder resulting from loss of function or tissue destruction of an organ or multiple organs, arising from humoral or cellular immune responses of the individual to their own tissue constituents. "Several studies have identified a link between THEMIS polymorphisms and autoimmune diseases that may contribute to metabolic dysfunction." (PMID 41282140, 2025). "As the thymus is likely to play a major role in early-onset autoimmune diseases, and the THEMIS gene contributes to the thymocyte selection in the thymus, we hypothesised that the underlying causal genetic variant would affect a regulatory motif active in thymocytes." (PMID 35986039, 2022). "We performed fine-mapping across the 6q22.33 region, which contains the adjacent PTPRK and THEMIS genes, and has never previously been associated with AAD or type 1 diabetes, but has been reported to be associated with susceptibility to other autoimmune diseases." (PMID 28983737, 2018).
type 1 diabetes (3 papers, 2018 to 2022). "We recently mapped a genetic susceptibility locus on chromosome 6q22.33 for type 1 diabetes (T1D) diagnosed below the age of 7 years between the PTPRK and thymocyte-selection-associated (THEMIS) genes." (PMID 35986039, 2022).
Autoimmunity (2 papers, 2018 to 2020). The occurrence of an immune reaction against the organism's own cells or tissues. "PTPRK and its neighbour THEMIS are required for early development of the thymus, which we can assume influences the initiation of autoimmunity." (PMID 28983737, 2018). "Interestingly, single nucleotide polymorphisms (SNPs) within the chromosome region containing THEMIS have recently been associated with younger age at T1D diagnosis, suggesting that alterations in this gene may contribute to aberrant thymocyte selection and thereby, autoimmunity." (PMID 32351504, 2020).
celiac disease (2 papers, 2012 to 2016). An autoimmune genetic disorder with an unknown pattern of inheritance that primarily affects the digestive tract. "Recently, a meta-analysis of genome-wide association data from celiac disease and Crohn's disease has identified several risk loci shared by both diseases, thus adding further support for common pathophysiological pathways and to the possible involvement of THEMIS in human IBD." (PMID 22275874, 2012). "Notably, an association between SNP rs802734 and coeliac disease has also been demonstrated, and subsequent investigations have shown that this SNP influences THEMIS, but not PTPRK, expression in treated coeliac disease patients." (PMID 27438997, 2016).
multiple sclerosis (2 papers, 2016 to 2022). A progressive autoimmune disorder affecting the central nervous system resulting in demyelination. "Our data suggest that the multiple sclerosis risk allele is associated with decreased THEMIS expression in human T-cells, and that this association is driven by differences in exon 1-containing THEMIS isoforms." (PMID 27438997, 2016).
Immunodeficiency (1 paper, 2022). Failure of the immune system to protect the body adequately from infection, due to the absence or insufficiency of some component process or substance. "It should be noted, however, that PTPRK is directly upstream of gene THEMIS (thymocyte-expressed molecule involved in selection), and rats that suffer from a co-deletion of both genes display defective T-cell maturation because of T-helper immunodeficiency." (PMID 36755664, 2022).
lymphoma (1 paper, 2022). A malignant (clonal) proliferation of B- lymphocytes or T- lymphocytes which involves the lymph nodes, bone marrow and/or extranodal sites. "Its role in T-cell leukemia/ lymphoma is largely unknown, but THEMIS was recently shown to be downregulated by promoter methylation in HTLV-1-infected CD4-positive cells of adult T-cell leukemia." (PMID 36376973, 2022).
T-cell neoplasms (1 paper, 2022). "In aggregate, these findings suggest that epigenetic deregulation of THEMIS may play a common role in the molecular pathogenesis of different T-cell neoplasms and thus deserves further investigation." (PMID 36376973, 2022).
tumor (3 papers, 2023 to 2024). "Similarly, the C4 subgroup was identified in the tumor tissues of the validation cohort, exhibiting a high similarity to CD4_THEMIS cells and expressing high levels of CBLB, THEMIS, and CAMK4." (PMID 38948071, 2024).
THEMIS also shares sentences with these, for which no sentence is quoted: infection (9 papers); cholera (2); abscess (1); acute pneumonia (1); bacteremia (1); cancer (1); Crohn disease (1); Cutaneous abscess (1); hematologic malignancies (1); inflammatory bowel disease (1); liver disease (1); melanoma (1); skin infection (1); T-cell leukemia (1).